CD44 (CD44 molecule (IN blood group))
Diseases named in the same sentence as CD44 in open-access papers (continued):
Sharing a sentence is not in itself a finding about the gene and the disease.
breast carcinoma (continued). "The results from the current study indicated that patients with a higher frequency of CD44-/CD24- cells in their breast cancer tissues had a high risk to develop delayed distant metastasis 5–7 years after diagnosis." (PMID 34318746, 2021). "Based on the existing studies, this study will systematically evaluate the relationship between CD44 gene rs13347 polymorphism and breast cancer." (PMID 34087833, 2021). "The association between CD44 gene rs13347 locus polymorphism and breast cancer has been paid attention by many scholars." (PMID 34087833, 2021). "Specifically, in the context of TNBCs, the expression of CD44 is linked to cancer stemness and linearly correlates with the amount of breast Cancer Stem Cells (CSCs) characterized by the CD44high/CD24low immunophenotype." (PMID 34833068, 2021). "Expression and fluctuations of cell surface markers (e.g., CD44) have long been associated with metastatic progression in breast cancer." (PMID 34579762, 2021). "This study will provide evidence-based medical evidence to clarify the role of CD44 gene polymorphism in breast cancer, and provide help for the early detection and preventive intervention of breast cancer." (PMID 34087833, 2021). "Since the reported associations are diverse, additional studies with larger prospective cohorts are needed to further evaluate the association between CD44 expression and the prognosis of patients with breast cancer." (PMID 34944493, 2021). "The results indicated that higher frequency (≥19.5%) of CD44-/CD24- cells was associated with delayed postoperative breast cancer metastasis." (PMID 34318746, 2021). "High CD44 expression in breast cancer stem-like cells led to p62-associated Nrf2 elevation, possibly due to the activation of autophagy." (PMID 34322664, 2021). "At present, a number of studies have explored the relationship between rs13347 polymorphism of cluster of differentiation 44 (CD44) gene and breast cancer, but the research conclusions are inconsistent." (PMID 34087833, 2021). "More importantly, a higher frequency of CD44-/CD24- cells in breast cancer tissues was associated with significantly with worse DFS and delayed distant metastasis." (PMID 34318746, 2021). "The BRCA1 protein is involved in DNA repair mechanisms, and it has been demonstrated that BRCA1-deficient mouse mammary tumors are enriched in CD44+/CD24−/(low) and CD133+ cells." (PMID 34359928, 2021). "CD44 has also been linked to RhoGTPase actin cytoskeletal regulators, Rac1 and RhoA, in astrocytes as well as other systems such as breast cancer cells and keratinocytes." (PMID 33020512, 2020). "The regulation of cell adhesion was one of the major pathways altered in CD44 KO breast cancer cells, confirming other studies that have linked CD44 with cell adhesion." (PMID 32455980, 2020). "It is known that Nav1.5 expression in breast cancer cells is closely associated with the protein level of CD44, which correlates with poor outcomes of breast cancer." (PMID 32792949, 2020). "For example, Zolkiewska and colleagues found that selumetinib blocked EGF-induced expansion of CD44+/CD24– breast cancer stem cell associated populations." (PMID 32391382, 2020). "The results from this study suggest that CD44 is clinically associated with stage of breast cancers." (PMID 32986353, 2020). "Using RNA sequencing approaches, we found that loss of CD44 in breast cancer cells altered the expression of cytokine-related genes." (PMID 32455980, 2020). "In breast cancer, CD44 alternative splicing causally contributes to EMT cancer progression by activating PI3K/AKT pathway." (PMID 32939931, 2020). "Due to the association between HA-CD44 interactions, we investigated CD44 as a novel regulator of inflammatory cytokines within breast cancer cells." (PMID 32455980, 2020). "For example, CD44 was reported to be a specific breast cancer stem cell marker, but CD44 has diverse splice variants." (PMID 35692625, 2020).
breast carcinoma (continued). "For example, a switch from the CD44 variant isoform (CD44v) to the CD44 standard isoform (CD44s) is functionally essential for epithelial-mesenchymal transition and determines breast cancer stem cell state and metastasis 15-17." (PMID 32373210, 2020). "FOXP2 negatively regulates stem cell-associated factors—such as c-MYC, OCT-4, and CD44—in breast cancer, resulting in a putative tumor/metastasis suppressor." (PMID 31936744, 2020). "Examination of mesenchymal markers revealed that IFN-β not only inhibited the OSM-mediated expression of CD44, but also prevented repression of Claudin-1 and E-cadherin (epithelial markers associated with less aggressive breast cancers)." (PMID 31036052, 2019). "While not necessarily a passenger mutation, the discovery of the PROCR gene being specific to CD44+ breast cancer cells creates a better understanding of the cellular mechanisms and pathways activated in breast cancer." (PMID 31379741, 2019). "The expression of LKB1 has shown its association with CD44, which is a marker of stemness in breast cancer stem cells." (PMID 30696074, 2019). "Another experimental model focusing on tumor heterogeneity in breast cancers identified a subclonal genetic marker associated with CD44+ breast cancer stem cells." (PMID 31379741, 2019). "hnRNPM is associated with increased standard form of CD44 (or CD44 standard, CD44s) in aggressive breast cancer patient specimens." (PMID 31737791, 2019). "Accordingly, EV-associated CD44 has been linked to tumor progression and resistance to treatment in breast cancer and myeloma, respectively." (PMID 31453379, 2019). "It has been reported that breast cancer stem-like cells expressing CD44 variant isoforms exhibited enhanced metastatic capacity." (PMID 31416894, 2019). "In breast cancer, the expression of CD44 and CD24 has been linked to the identification of cancer stem cells, therapeutic responses, and the invasive behavior of tumor cells." (PMID 31357721, 2019). "The cell surface marker CD44 has been associated with stem-cell-like characteristics and poor clinical outcome in breast cancer." (PMID 31627418, 2019). "The intracellular domain of CD44 (CD44-ICD) has been implicated as a co-transcription factor for RUNX2 in the regulation of expression of MMP-9 in breast carcinoma cells." (PMID 31331331, 2019). "The risk of breast cancer related to CD44 polymorphism was further examined with stratification by age, family history of breast cancer, pathological type, clinical stage, estrogen/progesterone receptor status (ER, PR), and Her2 expression." (PMID 29483847, 2018). "Given that CD44 has 9 variant exons and the regulation of the expression of these exons is complex, SALL4‐regulated KHDRBS3 expression seems to be one of the factors for CD44 variant expression in basal‐like breast cancer." (PMID 29356399, 2018). "The results revealed that the expression of AR was significantly associated with let-7a and CD44+/24-/low especially in estrogen receptor positive (ER+) breast cancer tissues." (PMID 29423076, 2018). "Breast cancers with high CD44 and low CD24 have been associated with the triple negative subtype (negative for estrogen receptor (ER), progesterone receptor (PR), and HER2 receptor) and with poorer prognosis." (PMID 29600163, 2018). "Loss of E-cadherin in breast cancer cells is associated with increased CD44 expression and stemness." (PMID 30271576, 2018). "Nonetheless, a number of studies have shown that CD44 expression is preferentially associated with the undifferentiated or progenitor-like phenotype whereas CD24 is expressed in more differentiated breast cancer cells with a luminal phenotype." (PMID 29510720, 2018). "In another study, a significant association was observed between the same CD44 polymorphism and breast cancer risk in the population, European descent and African–American." (PMID 29483847, 2018).
breast carcinoma (continued). "Since CD44 alternative splicing and overexpression implicated in tumor progression, more experiments should be performed to determine the probable effects of A > G polymorphism on CD44 expression in patients with breast cancer." (PMID 29483847, 2018). "The current study found that A > G polymorphism in intron 1 of CD44 was associated with higher grades of breast cancer, and generated a new SC35 binding site as predicted by the ESE finder." (PMID 29483847, 2018). "A recent report clearly showed that CD44 splicing isoform-switching from variant isoforms (CD44v) to the standard isoform (CD44s) in tumor epithelium occurs during EMT in breast cancer progression." (PMID 30042817, 2018). "CD44 has been shown to be palmitoylated and inhibiting CD44 palmitoylation through cysteine point mutations strongly enhanced breast cancer migration." (PMID 29648538, 2018). "In this study, CD44‐positive (CD44+Fbs) and CD44‐negative carcinoma‐associated fibroblasts (CD44−Fbs) were isolated and cocultured with breast cancer cells for analysis of cell survival and drug resistance." (PMID 28523716, 2017). "Epithelial-mesenchymal transition is associated with CD44 high/CD24 low-expressing breast cancer stem and stem-like cells, and CD44 was part of the GSEA Hallmarks EMT gene set found enriched among the differentially expressed genes in DIP2C−/− cells." (PMID 28716088, 2017). "It is possible that CD44 expression in breast cancer is associated with highly aggressive breast tumour subtypes or highly invasive breast cancer cells." (PMID 29190904, 2017). "Overall, our findings indicate the association of intratumor morphological heterogeneity in breast cancer with the epithelial-mesenchymal transition and CD44+CD24- stemness and the appeal of this heterogeneity as a model for the study of cancer invasion." (PMID 28977854, 2017). "Several studies have demonstrated that overexpression of CD44 protein was associated with poor prognosis in colorectal carcinoma, breast cancer, and gastric cancer." (PMID 29445738, 2017). "As CD24 expression is often associated with CD44 expression in breast cancer cells, we analyzed CD44 cell surface expression in Mvt1-derived scrambled and ATF5-KD cells." (PMID 28785242, 2017). "We report the physical association of CD74 and CD44 and consider their likely function in breast cancer cells." (PMID 29190904, 2017). "V6 variant of CD44 has been proved to correlate with a bad prognosis in Hodgkin's lymphoma, colonic, cervical, gastric, and breast cancer." (PMID 28326100, 2017). "Although both CD44 splice isoforms (CD44s and CD44v) play essential roles in breast cancer development, CD44v is more associated with favorable prognosis, such as luminal A subtype, while CD44s is related to poor prognosis, such as HER2 or basal cell subtypes." (PMID 28881705, 2017). "A recent study suggests that breast cancer models show the expression of CD44 standard and variant isoforms which increase disease-progressing and metastatic behavior." (PMID 28326306, 2017). "The CD44+/CD24−/low phenotype is more associated with basal-like breast cancers, while the ALDH1+ cells are more common in HER2-overexpression (HER2-OE) and basal/epithelial breast cancers." (PMID 29062075, 2017). "Fillmore C. and Kuperwasser C. supposed that CD24+ population was mainly characterized by less differentiated basal type of breast cancer, and CD44+ cells caused the development of luminal form of breast cancer, being more differentiated type of tumor." (PMID 28622715, 2017). "All of this is supported by the findings of co-expression of HIF-1α and the CD44+/CD24−/low phenotype (self-renewal ability) associated with worse prognosis of breast cancer patients." (PMID 29099748, 2017). "Recently, overexpression of CD44 was associated with significantly worse overall survival in breast cancer patients." (PMID 28279210, 2017).
breast carcinoma (continued). "The presence of CD44+ CTCs is linked to bone metastasis and correlates with poor prognosis in breast cancer." (PMID 27220365, 2016). "High expression of CD44 has been associated with human breast cancer stem cells as well as with HMLE cells that have undergone EMT." (PMID 26930717, 2016). "In human breast cancer, the CD44+/CD24−/low CSCs signature was linked with a mesenchymal, migratory phenotype." (PMID 27313840, 2016). "Our results demonstrate that WNT5A signaling affects the expression of the transmembrane glycoprotein CD44, and WNT5A is known to alter the splicing of CD44 and its variant isoforms in breast cancer." (PMID 27623766, 2016). "For example, in breast cancer the EMT state has been associated with cancer stem cell properties including the expression of stem cell-associated CD44+/CD24-/low antigenic profile, self-renewal capabilities and resistance to conventional therapies." (PMID 27102300, 2016). "In patients with breast cancer undergoing neoadjuvant therapy, there was an increase of CD44+/CD24− cells expressing EMT-associated genes found in the post-treatment biopsy." (PMID 27429011, 2016). "In accordance with the reported positive association between CD44 and breast cancer metastasis, the migration and invasion of breast cancer cells significantly impaired in our siRNA-CD44 knockdown experiments." (PMID 27623766, 2016). "The data from different research groups have revealed that WNT5A expression in clinical breast cancer samples is marker of good prognosis, whereas CD44 expression has been associated with poor prognosis." (PMID 27623766, 2016). "CD44+ cells are associated with the most clinically aggressive breast cancer subtypes (triple-negative and HER2-enriched)." (PMID 26673618, 2016). "Understanding the mechanisms involved in c-Src-regulated Twist signaling and the subsequent expression of miR-10b is critically important for elucidating the mechanisms involved in HA/CD44-associated breast cancer metastasis." (PMID 27070574, 2016). "Association of CD44 expression and clinical prognosis of patients has been studied in diverse malignant tumors, such as colon and breast cancer." (PMID 26079799, 2015). "Next, we used a reporter assay of a luciferase promoter of CD44, one of Wnt signaling pathway's downstream targets which was associated with breast cancer stem cell metastasis and AML stem cell homing." (PMID 26079538, 2015). "miRNAs are secreted from malignant breast epithelial cells after packaging into vesicles larger than conventional exosomes that are enriched in CD44, whose expression is linked to breast cancer metastasis." (PMID 26132860, 2015). "CD44 expression is up-regulated in high-grade human breast tumors, and causally contributes to the epithelial-mesenchymal transition and breast cancer progression." (PMID 26079799, 2015). "Experimental studies in breast cancer models support that expression of standard and variant isoforms of CD44 increases disease-progressing and metastatic behavior." (PMID 25888636, 2015). "Among tested breast cancer cell lines, paclitaxel-induced increases of Snail were the highest in MDA-MB-231 and Hs578T cells, which are highly invasive breast cancer cell lines, associated with cancer stem-like features (CD44+/CD24−)." (PMID 26462028, 2015). "A major challenge in the mechanistic understanding of HA in breast cancer-associated inflammation is to link HA metabolism with specific contributions of HA receptors CD44, RHAMM, and LYVE-1, which are all expressed by macrophages." (PMID 26106384, 2015).
breast carcinoma (continued). "For identification of stem cell phenotype, many studies showed that high levels of CD44 associated to low levels of CD24 (CD44(+)/CD24(−/low)) would characterize stem populations in breast cancer." (PMID 26504780, 2015). "To further understand the role LSR and CD44 play in breast cancer susceptibility to iota toxin, we evaluated the effects of toxin exposure over time." (PMID 24990559, 2014). "That said, our findings vis-à-vis the association between extra-raft CD44 and invasion/migration are broadly supported by data in primary cultures from breast cancer patients." (PMID 24512624, 2014). "In this study, we examine the effect of NF-κB inhibition on CD44 expression and the activities associated with CD44 dysregulation, including cell proliferation and invasiveness in breast cancer cells." (PMID 25184276, 2014). "There is an inverse correlation between ER and Sox2 expression in breast cancer cells and an association between the CD44+CD24−/low phenotype of tamoxifen-resistant breast cancer cells and Sox2 expression." (PMID 24178749, 2014). "The anti-CD44 phage antibodies with the highest affinities were converted to full length IgG which were used to stain breast cancer cell lines, and to detect specific variant in the breast tumor sections." (PMID 25353955, 2014). "Recently, our group demonstrated that P-cadherin expression is associated with breast cancer stem cell markers, namely CD44, CD49f and ALDH1." (PMID 25269858, 2014). "We now report that loss of WISP2 in MCF7 breast cancer cells can also promote the emergence of a cancer stem-like cell phenotype characterized by high expression of CD44, increased aldehyde dehydrogenase activity and mammosphere formation." (PMID 24498388, 2014). "Despite expressional correlations of CD44 or its splice variants with progression of aggressive breast cancers, specific mechanisms of CD44-dependent cell migration remain controversial." (PMID 24512624, 2014). "We also observed that the expression of the CD44 rs13347 polymorphism in breast cancer patients in a previous study differed from that in OSCC patients in our study." (PMID 24699672, 2014). "Consistent with the induction of Snail1 and Twist, ectopic NKG2D–DAP10 expression (constitutive or Dox-induced) was associated with breast cancer stem cell-like CD24−/CD44+ profile shifts in the MCF-7–TF, MCF-10AT–TF and SUM149PT–TF lines." (PMID 25291178, 2014). "In the present study we dissected the relationship between CD44 raft affiliation, ezrin association and migratory potential in breast cancer cells." (PMID 24512624, 2014). "Based on gene expression profiles, basal-like breast cancers have been associated with the surface marker expression CD44+/CD24-/low while luminal epithelial cells have been associated with CD24+/CD44- expression." (PMID 24229464, 2013). "Two polymorphisms within the CD44 gene were studied to investigate the association of genetic variants with breast cancer risk prediction and prognosis." (PMID 23940692, 2013). "In breast cancer others have shown that the down-regulation of CD44 expression, a marker of breast cancer stem cells, was linked to increased sensitivity to doxorubicin treatment." (PMID 23874993, 2013). "The CD44 high/CD24 low phenotype in breast cancer cell has been linked to EMT through the mesenchymal attributes of breast cancer stem cells, which also have dramatically enhanced malignant properties." (PMID 26237148, 2013). "Another study published by same author in 2012, identified 4 SNPs in exon 2 through sequencing and found significant association of the CD44 polymorphisms in exon 2 coding sequence with higher probability and higher cumulative risk for breast cancer." (PMID 23940692, 2013). "Next, we performed a multivariate analysis using a logistic regression to evaluate the correlations of both the CD44 gene polymorphisms with the clinicopathological features and breast cancer treatment response to NACT." (PMID 23940692, 2013).